CRP (C-reactive protein)
Diseases named in the same sentence as CRP in open-access papers (continued):
Sharing a sentence is not in itself a finding about the gene and the disease.
osteoarthritis (continued). "The clinical applicability of our findings is emphasized by the potential for monitoring BMI or CRP levels in patients with osteoarthritis, as this strategy could assist in preventing complications associated with the comorbidity of osteoarthritis and chronic pancreatitis." (PMID 39568811, 2024). "For example, indicators such as C-reactive protein (CRP) and lactate dehydrogenase (LDH) can be used as auxiliary diagnostic markers for osteoarthritis; gene sequencing can identify genetic factors related to osteoarthritis, thus achieving early prevention and intervention." (PMID 37486949, 2023). "Previous studies have shown that inhibiting TNF-α in RA reduces local osteoarthritis through a reduction in synovial cell infiltration and the expression of adhesion molecules, chemokines, and cytokines, coinciding with reduced levels of acute phase reactants such as CRP and interleukin (IL)-6." (PMID 34209821, 2021). "CRP may be a marker for disease progression in osteoarthritis in people and dogs." (PMID 29920524, 2018). "Furthermore, serum CRP correlates with synovial fluid CRP as well as severity of osteoarthritis." (PMID 27757198, 2016). "The levels of ESR, CRP, WBC and Neutrophils count were increased in patients with osteoarthritis compared with healthy controls (P < 0.05)." (PMID 38167456, 2024). "Considering the consistency of CRP, ESR and FAR, the distinction can be explained by the fact that inflammation levels in spondyloarthritis patients are higher than in osteoarthritis patients and healthy controls." (PMID 36109740, 2022). "The main purpose of our study was the assessment of the effect of spa treatment on changes in concentration of TAS, CRP, and PRL in patients with osteoarthritis." (PMID 32373171, 2020). "The purpose of our study was the assessment of the effect of spa therapy, consisting of peloid therapy, physical therapy, kinesiotherapy, and radon water, on changes in concentration of TAS, CRP, and PRL in patients with osteoarthritis." (PMID 32373171, 2020). "In this pilot study, NP 06-1 had beneficial effects on symptoms of osteoarthritis of the knee as measured using LAI scores and had anti-inflammatory effects as measured using CRP." (PMID 19682376, 2009). "In summary, the effects of etoricoxib on CRP, LDL-C, homocysteine, and fibrinogen were comparable with those of placebo, celecoxib, and ibuprofen in patients with osteoarthritis." (PMID 20157362, 2008). "The study cohort included 44 patients with total knee/hip arthroplasty (16 with PJI, 8 with low-grade PJI with low α-defensin/CRP levels, 20 with osteolysis/aseptic loosening) and 64 controls with osteoarthritis with/without infection (OA-INF/OA: 28/36)." (PMID 41904372, 2026). "Early studies suggested an association between C-reactive protein levels and worse osteoarthritis progression; however, recent literature has shown that CRP and the platelet-to-lymphocyte ratio (PLR) are not strongly associated with osteoarthritis." (PMID 37284646, 2023). "C-reactive protein (CRP), a biomarker of inflammation, is highly expressed in osteoarthritis- (OA-) related diseases, but its exact role remains unknown." (PMID 35047645, 2022). "In the study of knee arthritis and osteoarthritis models, it was found that the level of serum CRP was not only related to the development and prognosis of the disease, but also positively correlated with pain intensity." (PMID 36368914, 2022). "As for osteoarthritis and DM, the top 5 most related genes were INS, TNF, IL-6, CRP, and IL-1B." (PMID 35719662, 2022). "For instance, while one study reported that vitamin D supplementation/maintaining sufficiency did not have a significant impact on CRP in individuals living with osteoarthritis, another study reported a significant reduction of CRP and surgical pain." (PMID 35057447, 2022).
osteoarthritis (continued). "Similarly, compared with HCs or patients with osteoarthritis, serum resistin levels were increased in patients with RA and positively correlated with inflammatory markers such as ESR, CRP, and disease activity, which determined by measuring disease activity score 28 values." (PMID 35592858, 2022). "Since eucalyptus oil has been reported effective in reducing pain and suppressing inflammation in the various animal models, we tested whether inhalation of eucalyptus oil affected pain, blood pressure, heart rate, CRP concentration, and WBC count following TKR in patients with osteoarthritis." (PMID 23853660, 2013).
melanoma (108 papers, 1994 to 2026). A malignant, usually aggressive tumor composed of atypical, neoplastic melanocytes. "The biomarker analysis of Checkmate76K phase III trial announced that the lower CRP levels at the serum were associated with longer RFS with adjuvant nivolumab in stage IIB/IIC melanoma." (PMID 40226614, 2025). "Data for this study were obtained from the IEU Open GWAS project website for genome-wide association study data (GWAS) on interleukin-6, C reactive protein levels and malignant melanoma." (PMID 38952546, 2024). "H3Cit, a biomarker of NETs, predicts the risk of mortality in patients with cancer, and elevated baseline serum IL-8 and CRP levels were associated with adverse outcomes in melanoma, NSCLC, and RCC." (PMID 37580733, 2023). "Levels of SAA also correlate with outcomes in patients with advanced melanoma and when combined with CRP show prognostic potential for identifying patients with high-risk early-stage melanoma." (PMID 34202272, 2021). "The outcomes of the present study underscore this aspect pertaining to melanoma patients with brain metastasis requiring surgery, as a preoperative CRP value of >10 mg/L was shown to be significantly associated with poorer overall survival." (PMID 33562331, 2021). "In a study of 95 patients with advanced melanoma treated with ipilimumab, decreased levels of CRP by the end of treatment were associated with better disease control and increased OS." (PMID 33924623, 2021). "They found that elevated CRP levels were associated with poorer overall survival and melanoma-specific survival." (PMID 34199802, 2021). "Most recently, the influence of preoperative inflammatory parameters (including CRP) on overall survival had been implicated in melanoma patients." (PMID 34381733, 2021). "CRP levels within normal range at baseline, and declining serum CRP between baseline and week 12 associated with better survival on ipilimumab in melanoma patients." (PMID 32258034, 2020). "A normal CRP level at the start of treatment was associated with longer OS for ipilimumab-treated melanoma patients." (PMID 30002656, 2018). "The biomarker signature consisting of TNFR-II, TGF-α, TIMP-1 and CRP is significantly prognostic of survival in patients with high-risk melanoma and warrants further investigation." (PMID 24457057, 2014). "Clinically, this CRP cycle appears to represent an underlying homeostatic oscillation in immunological reactivity in patients with advanced melanoma and ovarian cancer and possibly other malignancies." (PMID 19948067, 2009). "Several studies have suggested that IL-6 and CRP may be associated with diagnosis and prognosis of melanoma." (PMID 38952546, 2024). "In particular, the C allele in the rs17782313 SNP (within the melanocortin-4 receptor) was associated with increased BMI and poorer overall and melanoma-specific survival among patients with stage I/II melanoma, showing a trend towards the association with elevated CRP." (PMID 34631264, 2021). "CRP levels are recognized markers of inflammation, and several studies have identified high CRP levels (>10 mg) to be associated with an adverse prognosis in melanoma." (PMID 32027447, 2020). "SAA combined with C reactive protein might be used as prognostic serological biomarkers in early-stage melanoma patients, helping to discriminate low-risk patients from high-risk patients needing adjuvant treatment." (PMID 20957082, 2010). "Moreover, other data indicate that CRP>10 mg/L is possibly linked to resistance to IL-2 therapy, and it is possible that genetic variations underlying overweight and elevated CRP also contribute to worse melanoma patient survival." (PMID 37873776, 2023). "The single upregulated protein in native serum overlapped with all the other native and depleted blood samples and is C-reactive protein (CRP), which is a well-established, yet unspecific, melanoma biomarker." (PMID 38353833, 2024).
melanoma (continued). "In a study of 1144 melanoma patients (587 initial and 557 confirmed), CRP was found to be an independent prognostic marker in melanoma patients." (PMID 38952546, 2024). "A study has shown that high levels of CRP induce an immunosuppressive milieu in melanoma and supports blocking CRP as a therapeutic strategy to augment cancer immune checkpoint therapies." (PMID 38952546, 2024). "In melanoma patients, high serum concentrations of C-reactive protein (CRP) and the proinflammatory cytokine IL-6 before start of PD-1 blockade therapy correlate with poor treatment outcome." (PMID 38967829, 2024). "Elevated C-reactive protein (CRP) levels, an acute-phase protein that reflects systemic inflammation, have been associated with poorer prognosis in melanoma patients treated with ICIs, indicating a potential immunosuppressive environment." (PMID 39282490, 2024). "The measurements of CRP should be considered for inclusion in prospective studies of prognosis in melanoma patients and clinical trials of systemic therapy for melanoma patients." (PMID 38952546, 2024). "This led to strongly increased proteomic sensitivity, underscored by the detection of the melanoma biomarker CRP in differential abundance analysis of plasma and serum samples of only nine human subjects." (PMID 38353833, 2024). "A prospective study has shown that CRP can be used as a biomarker to assist immune checkpoint inhibitors in treatment of immune-related adverse events in melanoma patients." (PMID 38952546, 2024). "CRP has been used as an independent prognostic indicator in studies of a variety of diseases, including multiple myeloma, lymphoma, melanoma and ovarian, renal, pancreatic and gastrointestinal tumors." (PMID 38952546, 2024). "The goal was to explore the effect of interleukin-6 (IL6) and C reactive protein (CRP) on malignant melanoma (MM) using two-sample Mendelian randomization." (PMID 38952546, 2024). "One dog with oral malignant melanoma that had regional lymph node and lung metastasis (clinical stage IV) and a plasma CRP level of 115 mg/L, died within seven days of the first visit." (PMID 37009523, 2023). "We identified the lymphocyte-to-monocyte ratio (LMR) and C-reactive protein (CRP) to be the strongest predictors for melanoma recurrence." (PMID 36765660, 2023). "In summary, our data suggest that CRP in combination with LMR should be considered as a marker for melanoma recurrence in stage III melanoma patients with microscopic SLN metastasis." (PMID 36765660, 2023). "Melanoma-associated antigens (MAAs), microRNAs (miRNAs), S100B, CRP, LDH, and circulating tumor cells (CTCs) are possible biomarkers for the diagnosis of melanoma." (PMID 37292567, 2023). "Data from CheckMate 064, 066 and 067 also found that elevated levels of IL-6 and CRP played both an indirect and a direct suppressive role, accounting for the poor outcomes of melanoma patients receiving single agent and combination checkpoint inhibition." (PMID 35185894, 2022). "Clinical research on checkpoint inhibitors had previously found that elevated CRP levels negatively correlated with clinical outcomes for melanoma when treated with checkpoint inhibitors." (PMID 35185894, 2022). "Patients with melanoma displayed elevated CRP levels when irAEs occurred, and patients with a CRP level more than twice the ULN were more likely to have irAEs than those with a CRP level less than the ULN." (PMID 35756643, 2022). "The predictive role of IL-6 and CRP has also been proposed in melanoma and triple-negative breast cancer." (PMID 33777757, 2021). "Melanoma patients with an admission CRP ≤ 10 mg/dL achieved a significantly increased OS compared to patients with a preoperative CRP > 10 mg/dL (p = 0.002)." (PMID 33562331, 2021). "The CRP used in these studies was reported to be toxic to the lymphocytes themselves while still somehow being able to contribute to anti-melanoma activity." (PMID 34552600, 2021).
melanoma (continued). "Recently, the correlation between the baseline IL-6 and CRP in melanoma treated with immune checkpoint inhibitors (ICIs) or chemotherapy was demonstrated, and higher levels of IL-6 were significantly associated with poor survival." (PMID 33531609, 2021). "When peritoneal exudate macrophages from mice were exposed to CRP/liposomes, tumoricidal activity was generated against syngeneic T241 fibrosarcoma and B-16 melanoma cells, and against allogeneic Sarcoma-1 cells." (PMID 34552600, 2021). "Through retrospective analysis of 72 melanoma patients, they observed how in patients that experience irAE, the median serum CRP-levels exceeded the ULN (5 mg/L)." (PMID 33925387, 2021). "CRP is synthetized in response to cytokines such as interleukin-6 (IL-6), which is produced by melanoma cells." (PMID 32631431, 2020). "The present study is the first one that evaluated the relation between antiganglioside antibodies and IL-8 and CRP, based on their role in melanoma diagnosis, progression, and outcome, in metabolic disorders." (PMID 32855975, 2020). "Based on these accumulating data, we have investigated antiganglioside antibodies in correlation with other inflammatory markers (IL-8, CRP) and the clinical evolution of the melanoma patients." (PMID 32855975, 2020). "Nowadays, CRP is considered a true marker for assessing inflammation in melanoma, as well as a marker for response to treatment." (PMID 32855975, 2020). "To evaluate if the presence of IgM antibodies was associated with melanoma development, we determined their relation to inflammatory factors (IL-8 and CRP) recommended by AJCC for melanoma staging." (PMID 32855975, 2020). "Serum levels of several proteins, such as S100β, CRP, melanoma inhibitory activity (MIA) protein and LDH have been suggested as early biomarker candidates, but they do not seem to improve patient sub-classification into specific prognostic groups." (PMID 31803364, 2019). "Anti-PD-1 antibody-containing regimen was safe and effective in Chinese patients with advanced melanoma, and elevated CRP and ECOG score were independent factors predicting the efficacy of anti-PD-1 therapy." (PMID 31662753, 2019). "We challenged our data interpretation and other data for periodicity in either serial daily CRP measurements in melanoma patients, or in gynaecological cancer patients with less frequent measurements." (PMID 30400835, 2018). "We demonstrate that CRP enhances the cytotoxicity of peripheral blood mononuclear cells (PBMC) against melanoma cells in an in vitro model." (PMID 30450100, 2018). "MIA serum concentration represents an independent predictor for melanoma patients’ survival, while an increase in serum CRP is considered a sign of melanoma progression." (PMID 27461275, 2016). "The sensitivity and specificity of the predictive prognostic value of CRP were reported in only four studies, two in melanoma, one each in cancer of the esophagus and lung." (PMID 26717416, 2015). "Other inflammatory markers, as CRP and galectin-3, were prior correlated in melanoma with an increase in LDH and circulatory markers such as S100 and MIA." (PMID 26504364, 2015). "In a preliminary study of melanoma and ovarian cancer patients, serum CRP levels oscillated about a mean with a periodicity (λ) of 7 days." (PMID 24957270, 2014). "The oscillation in serum CRP concentration with a period of 7 days has previously been reported in 15 late-stage advanced melanoma and 4 late-stage advanced ovarian cancer patients." (PMID 24957270, 2014). "For first detection of melanoma stage IV disease, serum CRP has been reported to be potentially superior to serum LDH measurement." (PMID 24457057, 2014). "In a study of 12 patients with melanoma, less than 50% showed possible time dependent CRP concentration profiles." (PMID 24957270, 2014). "Data support a role for high serum CRP as a marker of poor prognosis and of immune tolerance in advanced melanoma." (PMID 24457057, 2014).